CDH6 (cadherin 6)
Diseases named in the same sentence as CDH6 in open-access papers (continued):
Sharing a sentence is not in itself a finding about the gene and the disease.
papillary thyroid cancer (8 papers, 2018 to 2023). "Linc00941 was found to be a novel transforming growth factor beta (TGF-beta) target by recruiting cadherin 6, which subsequently enhanced papillary thyroid carcinoma metastasis." (PMID 34254950, 2021). "In papillary thyroid cancer, it was found that TGF-β induces the transcription of LINC00941, which upregulates CDH6, an oncogene that promotes metastasis and EMT by modulating cytoskeleton adhesions, which hinder autophagy." (PMID 36869839, 2023). "On the contrary, it has been demonstrated that Cadherin-6 (CDH6) drives EMT and cancer metastasis by restraining autophagy in papillary thyroid carcinomas (PTCs)." (PMID 29609629, 2018). "Previous studies have reported that CDH6 could be abnormally upregulated and promote epithelial mesenchymal transition (EMT) and cancer metastasis by attenuating autophagy in the context of papillary thyroid carcinomas." (PMID 34530820, 2021).
renal carcinoma (8 papers, 2013 to 2025). A carcinoma arising from the epithelium of the renal parenchyma or the renal pelvis. "In contrast, CDH6 levels have been associated with renal carcinomas with poor prognosis and metastasis." (PMID 33715292, 2021). "Of note, knocking down CDH17 and CDH6 caused similar effects in reducing the pro‐metastatic properties of ovarian and renal cancer cells, likely through the direct interaction of CDH17 with α2β1 integrin." (PMID 33715292, 2021). "In this report, we have identified and characterized CDH6 and associated integrins as having a key role in ovarian and renal cancer progression." (PMID 33715292, 2021). "According to its initial location, CDH6 was mainly implicated in renal carcinomas, where it correlates with lymph node invasion and metastasis." (PMID 31324051, 2019). "In addition, increased CDH6 expression has been reported in several malignancies (including nasopharyngeal, ovarian, oral squamous cell, and renal cancers) and is associated with lymph node metastases and a poor prognosis." (PMID 34530820, 2021). "From the very beginning, CDH6 was associated with high expression in renal carcinomas." (PMID 31324051, 2019). "For example, CDH6 knockdown decreases migration and invasion in ovarian and renal cancer cell lines, which was attributed to reduced AKT and ERK activation." (PMID 40877928, 2025). "Taken together, our results reveal a key role for CDH6‐promoted αIIbβ3/α2β1 integrin crosstalk in adhesion, invasion, and lung metastasis in ovarian and renal carcinoma." (PMID 33715292, 2021). "Here, we demonstrated the role of CDH6 in regulating metastatic progression of ovarian and renal cancer by promoting the crosstalk between αIIbβ3 and α2β1 integrins." (PMID 33715292, 2021). "CDH6 is also highly expressed in renal cancers (in 47% of clear cell and 66 % of papillary subtypes)." (PMID 33715292, 2021). "In summary, we provide strong evidence of the potential therapeutic value of disrupting the interaction between CDH6 and the αIIbβ3/α2β1 integrins in ovarian and renal cancer metastases." (PMID 33715292, 2021). "To assess the clinical relevance of CDH6 and αIIbβ3 integrin, we examined their expression and prognostic value in ovarian and renal cancer." (PMID 33715292, 2021). "Together, these results supported further investigation of CDH6 and αIIbβ3 integrin in ovarian and renal cancer." (PMID 33715292, 2021). "Interaction of αIIbβ3 with CDH6, and subsequent αIIbβ3 activation, promoted activation of α2β1 and cell adhesion in ovarian and renal cancer cells." (PMID 33715292, 2021). "In summary, the interaction between CDH6 and αIIbβ3 regulates α2β1‐mediated adhesion and invasion of ovarian and renal cancer metastatic cells and constitutes a therapeutic target of broad potential for treating metastatic progression." (PMID 33715292, 2021). "In our earlier studies, antibodies against CK20, EpCAM and CA19–9 were used to detect metastatic colon cancer cells and antibodies against CK18, CA9, and Cadherin 6 were used to detect renal cancer cells in lymph nodes." (PMID 30290760, 2018). "The parallel observed between thyroid tumors and renal carcinomas in terms of CDH6 and CDH16 expression would suggest that these tumor types share at least a part of the mechanisms governing tumor progression." (PMID 24069422, 2013). "In renal carcinomas, where CDH6 expression is considered an established tumor biomarker, higher levels of CDH6 are prognostic of tumor aggressiveness and poor outcome." (PMID 24069422, 2013). "We hypothesized that, in a similar way, CDH6 might bind and activate α2β1 integrin in ovarian and renal cancer cells, being an additional target for those mAbs." (PMID 33715292, 2021). "In additional, it has been reported that CDH6 could represent a successful therapeutic target for the treatment of ovarian and renal cancers." (PMID 34530820, 2021).
renal carcinoma (continued). "Thus, we investigated the effect of CDH6 silencing as well as integrin subunits αIIb and α2 on the homing capacity of ovarian and renal cancer cells in distant organs." (PMID 33715292, 2021). "Cadherin 6 (CDH6) is significantly overexpressed in advanced ovarian and renal cancers." (PMID 33715292, 2021). "Overall, CDH6 expression was higher in renal cancer samples than in normal kidney tissue." (PMID 33715292, 2021). "Encouragingly, it was reported that HKT288, a CDH6-targeting ADC, could cause tumor regression in ovarian and renal cancer." (PMID 34530820, 2021). "We have now investigated the expression levels and different molecular interactions of CDH6, CDH17, αIIbβ3, and α2β1 integrins in ovarian and renal cancer." (PMID 33715292, 2021). "We first investigated total and plasma membrane expression of CDH6 and CDH17, together with α2β1 and αIIbβ3 integrins, in different ovarian and renal cancer cell lines, using the HT29 colorectal cancer cell line as positive control for expression of CDH17 and α2β1 integrin." (PMID 33715292, 2021). "As there is no information about αIIbβ3 expression in ovarian or renal cancer, no functional link between CDH6 and αIIbβ3 has been previously investigated." (PMID 33715292, 2021). "Notably, our results suggest that blocking the CDH6–integrin interaction with either RGD‐specific mAbs or αIIbβ3 integrin inhibitors represents a promising therapeutic strategy for treating ovarian and renal cancer metastasis." (PMID 33715292, 2021).
cholangiocarcinoma (6 papers, 2018 to 2025). A carcinoma that arises from the intrahepatic biliary tree (intrahepatic cholangiocarcinoma) or from the junction, or adjacent to the junction, of the right and left hepatic ducts (hilar cholangiocarcinoma). "On the contrary, Goeppert and colleagues demonstrated that CDH6 was a putative tumor suppressor and that the downregulation of CDH6 was in fact associated with poor outcome in cholangiocarcinoma patients." (PMID 34530820, 2021). "CDH6, which helps maintain epithelial integrity in the endometrium, has been shown to be a putative tumour suppressor in cholangiocarcinoma." (PMID 30513694, 2018). "In summary, the preclinical pharmacology data indicate CUSP06 has promising therapeutic potential in treating CDH6-expressing malignant solid tumors including ovarian, renal, uterine cancer and cholangiocarcinoma, and in tumors that are CDH6-low, as well as CDH6-high." (PMID 40871070, 2025). "In addition, CUSP06 exhibited tumor regression or robust tumor growth inhibition in CDH6-positive cholangiocarcinoma and uterine cancer PDX models." (PMID 40871070, 2025). "CUSP06 exhibits excellent in vivo antitumor efficacy in CDH6-high or -low cell line-derived xenograft (CDX) or patient-derived xenograft (PDX) models from human ovarian, renal and uterine cancers, as well as cholangiocarcinoma." (PMID 40871070, 2025). "A single dose of 10 mg/kg CUSP06 significantly inhibited tumor growth in a CDH6-low cholangiocarcinoma PDX model (LD-2214, CDH6 H-score = 60) compared to the vehicle or IgG-T1000-e control groups (p < 0.005)." (PMID 40871070, 2025). "CUSP06 exhibits excellent in vivo antitumor efficacy ranging from tumor growth inhibition to tumor regression in CDH6-high or -low cell-line-derived xenograft (CDX) or patient-derived xenograft (PDX) models from human ovarian, renal and uterine cancers as well as cholangiocarcinoma." (PMID 40871070, 2025). "In addition, we evaluated the CUSP06 efficacy in CDH6-positive uterine cancer and cholangiocarcinoma PDX models, where the therapeutic potential of CDH6-targeted ADCs has not previously been demonstrated." (PMID 40871070, 2025).
gastric cancer (6 papers, 2021 to 2025). A primary or metastatic malignant neoplasm involving the stomach. "By analyzing gastric cancer (GC) patients in two independent cohorts, Luo and co-workers showed that cadherins CDH2, CDH6, CDH7 and CDH10 were significantly associated with a poor GC prognosis." (PMID 35631574, 2022). "However, in gastric cancer patients, the expression of CDH6 also demonstrates diverse degrees, ranging from undetectable low to moderate levels." (PMID 38656888, 2024). "Hence, we explored the role and function of cadherin-6 (CDH6) in the diagnosis and prognosis of gastric cancer." (PMID 34530820, 2021).
thyroid tumor (6 papers, 2013 to 2025). A benign or malignant neoplasm affecting the thyroid gland. "Noticeably, CDH6 expression was greatly enhanced in all thyroid tumor-derived cells as compared to the normal thyrocytes." (PMID 24069422, 2013). "Among the Id1 target genes, the Cadherin-6 (CDH6, also known as K-Cadherin) was strongly induced by Id1 in thyroid tumor cells." (PMID 24069422, 2013). "In this work, we investigated the ability of normal and tumor thyroid cells to activate the EMT program in response to transforming growth factor-β (TGF-β) and we explored the possibility that CDH6 is a TGF-β target during EMT in thyroid tumors." (PMID 24069422, 2013). "On the other hand, the remaining ability of thyroid tumor cells to further increase some of the EMT markers (e.g. CDH6) in response to TGF-β implies an incomplete transdifferentiation of the cells." (PMID 24069422, 2013). "In order to investigate the effect of the TGF-β in thyroid tumor progression and the possibility that CDH6 is one of the TGF-β targets, five different thyroid-derived cell lines were selected and used as a model." (PMID 24069422, 2013). "We have previously shown that CDH6 is strongly induced in thyroid tumor cells with an aggressive phenotype and presents mesenchymal features." (PMID 24069422, 2013). "In a recent microarray analysis, we found CDH6 as a target of Id1 in aggressive thyroid tumor cells." (PMID 24069422, 2013). "Overall, these observations provide novel information on the mechanism of the EMT program in tumor progression and indicate CDH6 as a potential regulator of invasiveness in thyroid tumors." (PMID 24069422, 2013). "Sancisi found that CDH6 was highly expressed in thyroid tumor patients and could be as a regulator of invasiveness in thyroid tumors." (PMID 31921296, 2019). "In this work, we explored the possibility that CDH6 is part of the EMT program in thyroid tumors." (PMID 24069422, 2013). "Based on these observations we can hypothesize a model in which RUNX2 is the major mediator of TGF-β signaling in controlling the expression of CDH6 in thyroid tumor cells." (PMID 24069422, 2013). "Overall, these data demonstrate that CDH6 expression is controlled by RUNX2 in thyroid tumor cells." (PMID 24069422, 2013). "This is in accordance with our observation that CDH6 is expressed mainly in thyroid tumor cells with an aggressive phenotype and localized at the invasive front of PTCs, and supports the idea that CDH6 may favor the spreading of tumors by changing the adhesion properties of the cells." (PMID 24069422, 2013). "Recently, we found Cadherin-6 (CDH6, also known as K-CAD) highly expressed in thyroid tumor cells that display mesenchymal features and aggressive phenotype, following the overexpression of the transcriptional regulator Id1." (PMID 24069422, 2013). "In A549 lung cancer cell line CDH6 was expressed and induced upon TGF-β treatment at levels comparable to the thyroid tumor cell lines." (PMID 24069422, 2013). "We also showed that CDH6 is strongly induced by TGF-β treatment both in normal and tumor thyroid cells, and that its expression accompanies invasiveness in human thyroid tumor patients." (PMID 24069422, 2013). "Overall, the data presented in this work indicate that CDH6 is a potential mesenchymal marker of the EMT program and suggest its potential role in controlling invasiveness of thyroid tumors." (PMID 24069422, 2013). "We showed that TGF-β signaling pathway is constitutively activated in thyroid tumor cells and suggested that RUNX2 and CDH6 is part of this pathway." (PMID 24069422, 2013). "We demonstrate that CDH6 is a new transforming growth factor-β (TGF-β) target and that its expression is modulated similarly to other EMT mesenchymal markers, both in vitro and in thyroid tumor patients." (PMID 24069422, 2013).
thyroid tumor (continued). "In this work, we show for the first time that CDH6 is a novel TGF-β target gene in thyroid cells, and we demonstrate that its expression is controlled by RUNX2, which we have recently shown to be an important mediator of aggressive phenotype in thyroid tumor cells." (PMID 24069422, 2013). "However, siRNA mediated RUNX2 ablation does not completely abolish the TGF-β effect on CDH6 expression suggesting that other TGF-β–dependent factors beside RUNX2 may be involved in controlling this gene in thyroid tumor cells." (PMID 24069422, 2013).
infertile (4 papers, 2020 to 2022). "In this study, we demonstrated for the first time that CDH6 reduction was associated with infertile endometrium during the receptive window." (PMID 32600462, 2020). "We examined the clinical relevance of CDH6 on receptivity by determining CDH6 immunostaining levels in mid-secretory phase endometrium from fertile and infertile patients." (PMID 32600462, 2020). "In conclusion, our study has provided evidence that CDH6 was abnormally reduced in infertile endometrium during the receptive window." (PMID 32600462, 2020). "Together, our data revealed that CDH6 was dysregulated in the endometrium from women with infertility and altered Ishikawa cell adhesive capacity." (PMID 32600462, 2020). "By contrast, the infertile endometrium showed a reduced level of CDH6 staining in the luminal and glandular epithelium compared to the fertile group." (PMID 32600462, 2020). "A significant reduction of CDH6 immunolocalization was recorded in the luminal and glandular epithelium of endometrium from women with infertility (P < 0.05) compared to fertile group respective cellular compartments in the mid-secretory phase." (PMID 32600462, 2020). "Studies show that the CDH6 gene is dysregulated in the endometrium of women with infertility." (PMID 35711794, 2022). "This study aimed to investigate whether CDH6 is dysregulated in the endometrium of women with infertility during the receptive window and the effect of CDH6 on endometrial adhesion and receptivity." (PMID 32600462, 2020). "Our immunohistochemistry data revealed that CDH6 was downregulated in the apical and lateral surfaces of the endometrial luminal epithelium in the infertile endometrium during the mid-secretory phase suggesting CDH6 affects both adhesion and integrity of the endometrial luminal epithelium." (PMID 32600462, 2020). "Several mechanisms can reduce CDH6 expression in the infertile endometrium." (PMID 32600462, 2020). "Overall our study suggests that CDH6 may be useful as a biomarker or treatment target for dysregulated receptivity in women with infertility." (PMID 32600462, 2020). "However, whether CDH6 is directly regulated by miR-223-3p in the infertile human endometrium is unknown." (PMID 32600462, 2020). "Similarly, CDH6 may be downregulated in infertile endometrium epigenetically by DNA methylation." (PMID 32600462, 2020). "However, there are no studies investigating the role of CDH6 on receptivity and infertility." (PMID 32600462, 2020).
asthma (3 papers, 2020 to 2025). "RAPGEF3 may work synergistically with another candidate gene, cadherin-6 (CDH6), to influence asthma risk." (PMID 39858200, 2025). "The AEC data show that Rap Guanine Nucleotide Exchange Factor 3 (RAPGEF3) gene might act in concert with another candidate gene, cadherin-6 (CDH6) gene, to jointly influence the risk of asthma." (PMID 31932625, 2020). "We also discovered the locus-locus interaction of DNAm levels of the CDH6 gene and RAPGEF3 gene might interact with each other to jointly predict the risk of asthma – which suggests the pivotal role of cell-cell junction in the pathological changes of asthma." (PMID 31932625, 2020). "Interestingly, the authors also discovered that the DNAm levels of the CDH6 gene and RAPGEF3 gene might interact with each other to jointly predict the risk of asthma, which suggests the pivotal role of cell–cell junctions in the pathological changes of asthma." (PMID 35055381, 2022).
glaucoma (3 papers, 2017 to 2023). Increased pressure in the eyeball due to obstruction of the outflow of aqueous humor. "Prioritized gene variants in our glaucoma case-control cohort supported possible causal roles in four genes for POAG (AQP5, FOXM1, SRFBP1 and CDH6) and three genes in PACG (LAMA2, ACACB and RGL3)." (PMID 36833422, 2023). "AQP5, SRFBP1 and CDH6 also revealed significant altered expression in glaucoma in expression datasets." (PMID 36833422, 2023). "In contrast to DKK1, the potential role of CDH6 in glaucoma pathogeneses is currently unclear." (PMID 28068412, 2017). "We identified multiple genes of interest with higher relative expression in glaucoma-related cell types; examples include NEFM, SYT2 expression in RGCs, AQP5 and KRT3 expression in corneal epithelial cells and CDH6 in ciliary muscle." (PMID 36833422, 2023). "Rare, deleterious SNVs in AQP5, SRFBP1, CDH6 and FOXM1 from POAG families and in ACACB, RGL3 and LAMA2 from PACG families were found exclusively in glaucoma cases." (PMID 36833422, 2023).
lymph node metastasis (3 papers, 2021 to 2024). "A previous study reported that the expression of CDH6 in oral squamous cell carcinoma was associated with lymph node metastasis and a poor prognosis." (PMID 34530820, 2021). "High levels of CDH6 were unrelated to age, sex, clinical stage, histological grade, lymph node metastasis, and distant metastasis." (PMID 34530820, 2021).
leukemia (2 papers, 2019 to 2022). A malignant (clonal) hematologic disorder, involving hematopoietic stem cells and characterized by the presence of primitive or atypical myeloid or lymphoid cells in the bone marrow and the blood. "Based on our MSC data, tumorigenesis driven by CDH6/YAP1/OCT4 interactions in DR MSCs may be similar to leukemia, causing blockage of cell differentiation in various stages of hematological development [[." (PMID 35356283, 2022).